VEGFA (vascular endothelial growth factor A)
Diseases named in the same sentence as VEGFA in open-access papers (continued):
Sharing a sentence is not in itself a finding about the gene and the disease.
retinopathy (353 papers, 2007 to 2026). "Two other SNPs in the VEGFA gene have been shown a borderline association with retinopathy, namely rs833068, and rs3024998." (PMID 35069435, 2021). "This explains why our results show not only significant associations with SNPs in the VEGFA gene with retinopathy by itself, but also with the dual complications DR/DNp for rs3024997 and rs833068 of the VEGFA gene." (PMID 35069435, 2021). "However, previous studies indicate the role of carrying the T allele of the rs3024998 polymorphism in the VEGFA gene in shaping the risk of microvascular complications, including retinopathy." (PMID 38139123, 2023). "VEGFA gene polymorphisms might prove useful as a prognostic marker for development of PXE-associated retinopathy leading to earlier therapeutic intervention in order to prevent loss of central vision." (PMID 23802012, 2013). "Five VEGFA sequence variants showed significant association with severe retinopathy in PXE." (PMID 23802012, 2013). "MiR-181a inhibits VEGFA expression directly, thereby impairing endothelial cell migration and tube formation in models of oxygen-induced retinopathy." (PMID 40002813, 2025). "The increased vascular permeability critically marks the retinopathy, while VEGFA can essentially drive the vascular permeability." (PMID 40469974, 2025). "BoNT/A treatment led to a decrease of pro-angiogenic factors, including VEGFA, highlighting the potential of BoNT/A as a therapeutic intervention for pathological angiogenesis in retinopathies." (PMID 38922557, 2024). "VEGFA produced during the relative hypoxia phase (P12–P17) is an important instigator of edema in retinopathy." (PMID 33908348, 2021). "While a focus in the development of new therapies to treat retinopathies has been on increasing the potency of anti-VEGFA therapy, the detrimental effects of long-lasting VEGFA suppression are now being recognized." (PMID 32312382, 2020). "These resultssuggested that miR-200b over-expression and VEGFA low-expression canreduce the expression of retinopathy-related proteins such as TGF-β1 and HGF,while also enhance the expression of PEDF protein." (PMID 28122882, 2017). "Theseresults indicated that miR-200b over-expression and VEGFAlow-expression can reduce the mRNA expression of VEGFA and retinopathy-relatedproteins such as TGF-β1 and HGF, and enhance the expression of PEDF mRNA." (PMID 28122882, 2017). "In murine oxygen-induced retinopathy model, hypoxic retina produces high levels of VEGFA, that results in abnormal outgrowth of new blood vessels that are characterized by bulging and the presence of anastomose-like structures leading to dilatation and leakiness." (PMID 32382040, 2020). "Here we demonstrate that blocking VEGFA-induced VEGFR2 pY949 signaling at any of several steps in the downstream pathway, leads to reduced vascular leakage in two independent retinopathy models, OIR and CNV." (PMID 32312382, 2020). "Upregulation of miR-203a-3p, which targets VEGFA and HIF-1, may decrease retinal neovascularization in the oxygen-induced retinopathy rat model." (PMID 36017322, 2022). "By challenging mouse models representing different steps in VEGFA/VEGF receptor 2 (VEGFR2)-induced vascular permeability, we show that targeting signaling downstream of VEGFR2 pY949 limits vascular permeability in retinopathy induced by high oxygen or by laser-wounding." (PMID 32312382, 2020). "In all experiments determination of different splice isoforms of VEGF-A (for example VEGFXXXa or VEGFA –XXXb) did not perform and is an aim of further investigation of retinopathy in OXYS rats." (PMID 21750722, 2011). "The present study aimed to investigate whether SPN can prevent hypoxia-induced retinal neovascularization via inhibition of HIF-1α/VEGF signaling pathway in a VEGFA secretion model of ARPE-19 cells induced by CoCl2 in vitro and a neovascularization rat model of oxygen-induced retinopathy in vivo." (PMID 28009852, 2016).
retinopathy (continued). "The stringent BRB of the retinal vasculature is not expected to be regulated by VEGFA, however, in ocular disease such as retinopathy, the BRB may be broken down; in accordance, proliferative retinopathies are characterized by increased transvessel flow and edema." (PMID 32312382, 2020).
cardiovascular disease (142 papers, 2005 to 2026). "However, patients with various cardiovascular diseases (CVDs) have been discovered to have high levels of vascular endothelial growth factor-A (VEGF-A), which is commonly associated with adverse disease prognosis and severity." (PMID 40429899, 2025). "VEGFA is upregulated by cardiomyocytes during inflammation, mechanical stress, and cytokine stimulation, and higher levels have been associated with a range of cardiovascular disease and poor cardiovascular outcomes." (PMID 37803875, 2023). "Despite these beneficial roles, VEGFA was also upregulated in several pathological disorders, including a range of cardiovascular diseases and tumors." (PMID 40224485, 2025). "VEGFA plays a functional role in mediating angiogenesis and is responsible for a variety of physio/pathological processes in cardiovascular diseases." (PMID 33946378, 2021). "Suppression of NDST1 in endothelial cells results in reduced responsiveness to VEGFA, which plays important role in cardiovascular diseases." (PMID 31156544, 2019). "We found that ANGPT2, PLAT (tPA), SERPINE1 (PAI-1), and VEGFA, which are involved in cardiovascular disease, were influenced in ADAM9 knockdown cells." (PMID 29118335, 2017). "Higher circulating levels of VEGFA have been previously detected in serum of patients with cardiovascular disease." (PMID 24736319, 2014). "Unlike sCD40L, VEGFA is not correlated to either days postpartum or blood pressure and has been detected at high concentrations in several cardiovascular diseases where it is associated with poor prognosis and disease severity." (PMID 38745664, 2024). "Furthermore, dysregulation among genes including Nox4, Cx43, PGC1α, VEGFA, and TSP1 are reported with increased risk of cardiovascular diseases." (PMID 37493006, 2023).
adenocarcinoma (83 papers, 1998 to 2025). A common cancer characterized by the presence of malignant glandular cells. "There was a very significant correlation between the concentration of CCL28 and that of VEGFA in the serum of adenocarcinoma patients (Pearson correlation = 0.54, p = 0.009, R square = 0.291)." (PMID 27250766, 2016). "The results were comparable: VEGFA and VEGFR2 patterns of expression were similar; VEGFD, FGF2 were significantly downregulated as in lepidic adenocarcinomas and MMP2 was also significantly downregulated." (PMID 29137669, 2017). "In human lepidic adenocarcinomas, VEGFA and VEGFR2 mRNA were weakly expressed and no VEGFR2 protein was detectable." (PMID 29137669, 2017). "Blocking VEGFA and VEGFR2 might contribute to the limitation of extra thoracic dissemination of lepidic-predominant adenocarcinomas in humans and animals." (PMID 29137669, 2017). "Comparatively, we did not see differences in VEGFA expression in human lepidic adenocarcinomas." (PMID 29137669, 2017). "The low mRNA expression of VEGFA and the absence of expression of VEGFR2 in lepidic adenocarcinomas suggest the lack of activation of the angiogenic pathway." (PMID 29137669, 2017). "Similarly, VEGFA was weakly expressed and VEGFR2 was not expressed in human lepidic adenocarcinomas." (PMID 29137669, 2017).
vasculopathy (76 papers, 2009 to 2026). "VEGFA is associated with several vascular disorders, with an emphasis on diabetic conditions." (PMID 40427019, 2025). "Based on these preliminary data, we suggest a potential therapeutic strategy against VEGFA involving miR-205-5p in proliferative eye-related vascular disorders." (PMID 40002404, 2025). "Additionally, importantly for SSc-related vasculopathy, KLF5 promotes angiogenesis through directly regulating VEGFA transcription." (PMID 31582779, 2019).
neurodegenerative disease (68 papers, 2011 to 2026). A disorder of the central nervous system characterized by gradual and progressive loss of neural tissue and neurologic function. "VEGFA has been discussed as a potential target for treating PD40 and a recent study suggests blocking of VEGFA to prevent blood–brain-barrier disruption, which has been implicated in several neurodegenerative diseases, including PD41." (PMID 36801900, 2023). "Vascular endothelial growth factor-A (VEGF-A) is an angiogenic factor with neuroprotective effects that has been associated with neurodegenerative diseases." (PMID 21573104, 2011). "However, the role of VEGFA in neurodegenerative disease is quite complex." (PMID 31332262, 2021). "Downregulation of ANG, VEGFA, SURF4, and NIPA1 suggests impacts on neurodegenerative diseases and metabolic disorders." (PMID 38681774, 2023). "VEGFA was suggested to play a role in neuroprotection via activating VEGF receptor 2 and neuropilin-1 in various neurodegenerative diseases, including ALS and mice with a homozygous deletion in the hypoxia response element of the VEGFA promoter exhibited classical ALS-like symptoms." (PMID 31252669, 2019). "Moreover, other proteins involved in the regulation of angiogenesis, such as vascular endothelial growth factor-A (VEGF-A), have been shown to play important roles in the remodeling of tendons and in their degenerative diseases." (PMID 24900996, 2014).
inflammation (52 papers, 2011 to 2026). Aberrant reaction of the microcirculation characterized by movement of fluid and leukocytes from the blood into extravascular tissues. "Additionally, brain inflammation caused by SARS-CoV-2 was considered to be related to VEGFA, which can facilitate the accumulation of inflammatory cells and regulate the angiopoietins II level." (PMID 35241045, 2022).
neurological diseases (47 papers, 2007 to 2025). "Despite VEGFA levels having been linked to several neurodegenerative and neurological disorders, their effects could be time dependent." (PMID 35625687, 2022).
metabolic disorders (36 papers, 2011 to 2025). "Metabolic disorders further impacted cell death and metastasis, in part by regulating FN1, VTN, ENO2, and VEGFA." (PMID 28211215, 2017). "Multiple groups have reported that stimulation of angiogenesis in adipose tissue of obese rodents by increasing angiogenic gene expression (e.g., VEGFA, VEGFB, FLT1, FOXO, Angiopoietin2) not only improves local adipose tissue function, but also counteracts systemic metabolic disorders." (PMID 34660572, 2021).
bacterial infection (30 papers, 2009 to 2025). "The results revealed that the expression of VEGFA decreased in HIF-1α knockdown cells compared to that in wild-type cells after bacterial infection." (PMID 36916939, 2023). "Specifically, this bacterial infection induces the expression of Angpt2, Tnf-A and VegfA at the mRNA and protein levels." (PMID 36874142, 2023). "To explore the involvement of the HIF-1α–VEGF signaling pathway in mammalian respiratory barrier dysfunction during respiratory bacterial infection, we examined the expression levels of VEGFA and HIF-1α in MLE-12 cells after bacterial infection for 6 h." (PMID 36916939, 2023). "In summary, the present study is the first to demonstrate that treatment with the S1PR2 antagonist (JTE013) enhanced TGFβ/Smad and Akt signaling and increased VEGFA, PDGFA, and GDF15 gene expressions in murine BMSCs with or without bacterial infection." (PMID 36834810, 2023).
hematological malignancies (29 papers, 2010 to 2025). "Herein, we investigated the cytotoxic activity of a novel, TRAIL-based chimeric protein AD-O51.4 combining TRAIL and VEGFA-derived peptide sequences, in hematological malignancies." (PMID 36387080, 2022).
heart disease (26 papers, 2009 to 2026). "A higher concentration of VEGFA was observed in patients with different classes of heart diseases and was correlated with disease severity, as well as unfavorable prognosis." (PMID 33946378, 2021).
benign tumors (21 papers, 1997 to 2025). "These beneficial effects of E2F1 deficiency in the ischemic heart were due to an upregulation of pro-angiogenic factors (i.e., vascular endothelial growth factor A, VEGF-A and placental growth factor, PIGF." (PMID 31921839, 2019).
CNS tumors (13 papers, 2012 to 2025). "To assess the gene expression profile of hypoxia-induced genes in brain and CNS tumours, we queried the oncomine database for the following genes; HIF1A1, VEGFA, MMP2, NEDD9, SOX4, and SOX9." (PMID 22570651, 2012).
psychiatric disorder (12 papers, 2016 to 2025). A disorder characterized by behavioral and/or psychological abnormalities, often accompanied by physical symptoms. "Plasma concentrations of MIP-1α (U = 567, p = 0.002) and VEGFA (U = 552, p = 0.005) were significantly higher in AUD patients with comorbid psychiatric disorder compared to those without psychiatric comorbidity." (PMID 35625687, 2022).
hematological cancers (11 papers, 2016 to 2025). "At the same time, targeting regulatory factors such as VEGFA, which play a key role in both solid tumors and hematological tumors, is expected to further expand the clinical application scenarios of CAR T-cell therapy and enhance its efficacy." (PMID 41226585, 2025). "We also observed increased concentrations of CCL2, CCL3, CCL4, VEGFA and IL-1β in Severe-Death hematologic cancer patients." (PMID 36700209, 2022). "VEGFA enhancer is demethylated in various hematopoietic cancers, resulting in higher gene expression." (PMID 34316716, 2021). "Collectively, this evidence suggests that targeted VEGFA has important clinical value in restoring CAR T-cell therapy sensitivity in both solid and hematological tumors." (PMID 41226585, 2025).
colonic polyps (5 papers, 2006 to 2023). "Tjalma and colleagues used vascular endothelial growth factor A (VEGF-A) and EGFR as targets and irdye800cw as a fluorescent agent for the detection of colonic polyps." (PMID 37781571, 2023).
Genetic disorder (3 papers, 2020 to 2023). "NKX2‐3 has hitherto not been linked to a genetic disorder but the gene is a strong candidate gene for intestinal varices as it is expressed in human intestinal microvascular cells where it regulates VEGFA and MADCAM‐1 signalling." (PMID 31498527, 2020). "Genetic disorder, environmental abnormalities, or both of them influence the outcome of CNC cells, and, severely, lead to deformities in craniofacial region.Moreover, VEGFA is required by CNC cells during the process of embryonic development." (PMID 33947308, 2021).
gynecological tumors (3 papers, 2022 to 2024). "Thus far, the benefit of combined VEGFA and immune checkpoint inhibition is seen in tumors that respond to single agent anti-VEGFA therapy such as HCC, RCC, CRC, NSCLC, and gynecologic tumors." (PMID 35577211, 2022). "One such PD-1-VEGFA-trap, AK112 (a humanized IgG1 bispecific anti-PD-1/VEGFA antibody), is currently being tested in multiple phase 2 clinical trials involving NSCLC, TNBC, and advanced gynecological tumors (NCT04736823, NCT05227664, NCT04870177)." (PMID 35577211, 2022).
female reproductive diseases (2 papers, 2020 to 2023). "On the other hand, previous studies have suggested that VEGFA variants may be associated with female reproductive diseases, and some neonatal populations have shown potential links between VEGFA and the consequences of prematurity, although these have not been consistently replicated." (PMID 37239335, 2023).
VEGFA also shares sentences with these, for which no sentence is quoted: retinal vein occlusion (184 papers); vitreous hemorrhage (96); neovascular glaucoma (84); POEMS syndrome (70); ulcer (66); Atrophy (57); acute myocardial infarction (47); glomerular disease (44); peripheral arterial disease (44); Anxiety (36); retinal edema (36); breast (34); ovarian hyperstimulation syndrome (33); acute respiratory distress syndrome (32); liver cirrhosis (32); Polypoidal choroidal vasculopathy (31); dengue (30); Lewis lung carcinoma (30); congestive heart failure (29); bronchopulmonary dysplasia (28); polyneuropathy (28); soft tissue sarcoma (28); Kaposi's sarcoma (27); limb ischemia (27); ocular hypertension (26); osteonecrosis (26); portal hypertension (26); cystoid macular edema (25); endocrinopathy (24); skin changes (24).
A further 1,204 diseases each share a sentence with VEGFA in 22 papers or fewer.